RB1 (RB transcriptional corepressor 1)
Diseases named in the same sentence as RB1 in open-access papers (continued):
Sharing a sentence is not in itself a finding about the gene and the disease.
retinoblastoma (continued). "In 1971 Knudson put forward his two-hit hypothesis, postulating that two rate-limiting mutational events in the retinoblastoma susceptibility gene (RB1) were required for tumor formation in retinoblastoma." (PMID 29124525, 2017). "They found that single nucleotide variants, insertions and deletions, are very rare beyond RB1 inactivation and that targeted therapies based on secondary alterations would probably have an effect on only some parts of the tumor in some retinoblastoma patients." (PMID 29124525, 2017). "Description of retinoblastoma patients with RB1 gene mutations." (PMID 29261756, 2017). "Retinoblastoma is a rare childhood cancer initiated by RB1 mutation or MYCN amplification, while additional alterations may be required for tumor development." (PMID 27126562, 2016). "In order to confirm that the retinoblastoma and brain tumors are clonal outgrowths of cells carrying mutations in both the rb1 and rbl1 gene, we dissected an eye exhibiting retinoblastoma development and a normal looking eye from the injected side of a MDKO tadpole." (PMID 27739525, 2016). "Furthermore, of 24 retinoblastoma tumors in which RB1 bi-allelic inactivating mutations were identified, the second allele was mutated by LOH in 58% of tumors with nonsense substitution and in 75% of tumors with methylation of the promoter." (PMID 25602518, 2015). "Third, the MIRC1 (miR-17-92) microRNA cluster, which can activate AKT in a variety of contexts, is amplified and linked to cell death suppression in human retinoblastoma, and its overexpression in retinal cells with Rb1 and p107 deletion promotes rapid retinoblastoma." (PMID 25907958, 2015). "In recent years, genetic characterization of retinoblastomas beyond loss of RB1 has provided multiple potential targets for therapeutic intervention, including the oncogenes KIF14, MYCN, E2F3, DEK, MDM4 and SYK, the tumor suppressor cadherin-11, and the oncomiR cluster 17∼92." (PMID 24901248, 2014). "To determine which E2F transcription factors could be associated with upregulation of FA genes, we studied also the mRNA expression levels of activating E2F genes (E2F1, E2F2, E2F3) in RB1-mutated retinoblastoma and in basal breast tumors." (PMID 25161863, 2014). "This provided additional evidence that the disrupted RB1/E2F-pathway in the RB1-mutated retinoblastoma tumors may play a role in upregulation of the FA/BRCA-pathway members." (PMID 25161863, 2014). "Interestingly, some subtypes of glioblastoma share common genetic abnormalities with retinoblastomas as mutations in the RB1 specific pathway are associated with the shortest survival in patients affected by glioblastoma." (PMID 24498108, 2014). "Based on our data, we suggested that STAT3 inhibition could be a potential therapeutic approach in retinoblastoma beyond the focus on aberrant cell cycle machineries related with RB1 gene mutation." (PMID 25359779, 2014). "Retinoblastoma, by virtue of its etiology requiring mutations of both RB1 genes, facilitates easy tracking of the origins of cells grown outside of the original tumor by sequencing the RB1 gene and comparing the results to clinical genetic sequencing of both the original tumor and the germline." (PMID 23826078, 2013). "More than 50% of retinoblastoma cases are sporadic and mainly caused by RB1 gene mutation." (PMID 23559850, 2013). "Detecting RB1 mutations could enhance the quality of clinical management of retinoblastoma in patients, and risk prediction for all members of affected families could be estimated." (PMID 23441118, 2013).
retinoblastoma (continued). "By contrast, those individuals in family #2 who inherited the mutant RB1 allele from their fathers displayed a reduced abundance of the nonsense transcript with six of eight carriers developing retinoblastoma, indicating that the mutant transcript has residual function." (PMID 23820649, 2013). "Zebrafish rb1te226a mutants harbor a human retinoblastoma causing rb1 gene mutation." (PMID 23209449, 2012). "Thus, sequence homology, syntenic conservation, and cDNA sequence analysis provide compelling evidence that space cadet phenotypes are caused by an rb1 gene mutation known to cause retinoblastoma." (PMID 23209449, 2012). "We propose that the unique retinal sensitivity to tumorigenesis induced by RB1 loss is primarily due to a barrier to apoptosis inherent in developing retina, consistent with the demonstration in mice that the cell of retinoblastoma origin is intrinsically death resistant." (PMID 22336108, 2012). "Following this observation, a RB1 mutation was identified in lipomas from hereditary Rb patients." (PMID 23036192, 2012). "Children diagnosed with the hereditary form of retinoblastoma (Rb), a rare eye cancer caused by a germline mutation in the RB1 tumor suppressor gene, have excellent survival, but face an increased risk for the development of sarcomas, both soft tissue (STS) and bone." (PMID 23036192, 2012). "Heritable retinoblastoma is caused by a mutation of the RB1 tumor suppressor gene." (PMID 22550413, 2012). "In human bilateral retinoblastoma, a germline mutation in one RB1 allele is typically observed, and the second allele undergoes somatic mutation, in agreement with Knudson's «two-hit hypothesis» for inherited cancer syndromes." (PMID 22761580, 2012). "Germline mutations in RB1 gene predispose carriers to retinoblastoma tumors, resulting from loss of heterozygosity, which is described in Knudson’s two-hit hypothesis." (PMID 21615945, 2011). "Although more than 90% of germline mutations in one RB1 allele in individuals may cause cancerous tumors of the retina, previous investigations show that some families have extremely low penetrance of retinoblastoma." (PMID 21615945, 2011). "This first report of RB1 gene screening in Moroccan patients with retinoblastoma shows a comparable mutational spectrum to those reported previously, which has evident importance for managing patients with retinoblastoma and their families." (PMID 22219649, 2011). "Clinical assessment and molecular analyses included the high resolution melting assay followed by DNA direct sequencing in an apparently sporadic index case with unilateral retinoblastoma, which led to identification of the c.1960 G>T mutation in exon 19 of the RB1 gene in this family." (PMID 21615945, 2011). "Mutations of the retinoblastoma (RB1) gene, which is the first tumor suppressor gene located on chromosome 13q14, regulates the cell-cycle G1/S check point, resulting in either malignant retinoblastoma or benign retinoma." (PMID 21615945, 2011). "Retinoblastoma is initiated by loss of both RB1 alleles, denoted M1 and M2 mutational events." (PMID 20421947, 2010). "Interestingly, a point-mutation in the −201/U-GCbox of the RB1 promoter was identified in a hereditary retinoblastoma family." (PMID 20614030, 2010). "Children with retinoblastoma often have a mutated RB1 allele and a null allele." (PMID 16231976, 2005). "Retinoblastoma (RB) is typically associated with highly penetrant pathogenic sequence variants (PSVs) in the RB1 gene; however, some families exhibit low penetrance RB (LPRB)." (PMID 41934609, 2026). "Retinoblastoma is the most common primary intraocular malignancy of childhood and may occur sporadically or as a heritable disease related to pathogenic variants in RB1." (PMID 42011192, 2026).
retinoblastoma (continued). "The retinoblastoma gene (RB1), which is located on chromosome 13q14.2, is mutated in retinoblastoma (RB), the most common malignant intraocular tumor in children." (PMID 41002743, 2025). "Notably, the coexistence of BRAF and RB1 mutations in RB‐68 may have resulted in stage E retinoblastoma and the patient underwent enucleation." (PMID 40317918, 2025). "Retinoblastoma (RB) is an aggressive pediatric malignancy originating from immature retinal cells, caused by bi-allelic inactivation of the Retinoblastoma 1 (RB1) gene." (PMID 41315216, 2025). "Furthermore, the cells carrying the germline mutation of RB1 might be a representative model for exploring the driving mechanism of osteosarcoma development in retinoblastoma patients." (PMID 38744935, 2024). "The first TSG Rb1 (retinoblastoma gene 1), which encodes the retinoblastoma protein that causes RB cancer development, was discovered by Knudson, influences cell survival and apoptosis through interactions with other nuclear proteins." (PMID 38167059, 2024). "Heritable RB is caused by a germline mutation in the retinoblastoma gene (RB1) followed by a second somatic mutation." (PMID 39724000, 2024). "Children with hereditary RB or those carrying a single copy of a mutated RB1 gene have an elevated risk of developing multiple retinoblastomas in both eyes during their early life." (PMID 38540335, 2024). "In addition, we were able to detect previously unknown somatic RB1 pathogenic variants in two retinoblastoma patients undergoing IViC treatment." (PMID 38672657, 2024). "Retinoblastoma is caused by the RB1 gene and has unknown prevalence." (PMID 39480826, 2024). "This cohort study aimed to retrospectively observe whether these factors influence the ratio of bilateral retinoblastoma cases compared to unilateral retinoblastoma, thereby inferring an influence on the development of de novo germline pathogenic variants in RB1." (PMID 35361938, 2023). "Although, mosaicism in an unaffected parent of a sporadic Rb patient is very rare around 0.7%, it is important to determine whether the mosaic pathogenic RB1 mutation happened before the zygote is formed (preconception mutation) or after it is formed (postconception mutation)." (PMID 37658463, 2023). "The study aimed to generate a stepwise method to reduce the workload of full-scale RB1 sequencing for germline mutation screening in retinoblastoma (RB) patients." (PMID 36173648, 2022). "We also highlight the case of a bilateral retinoblastoma associated with a RB1 complete deletion that despite a good response to intra-arterial chemotherapy as presented with multiple recurrences during the study period, which we hypothesize being related with the specific large deletion." (PMID 35288594, 2022). "Retinoblastoma (RB) is a rare pediatric intraocular malignancy arising from the biallelic mutation of the retinoblastoma gene (RB1)." (PMID 36096885, 2022). "Hence, our integrative bioinformatics and in vitro validation results suggest that the RB1 gene loss in retinoblastoma patients could provoke epigenetic events which in turn dysregulate the expression of E2F3 and thus promote Rb development in retinal cells." (PMID 35359459, 2022). "Retinoblastoma (RB) is the most common intraocular cancer of childhood arising due to the development of the mutation or the loss of one allele for the RB1 gene." (PMID 35631620, 2022). "The rare cancer retinoblastoma (RB) is an aggressive and the most common intraocular cancer in children, mainly caused by mutations in the tumor suppressor gene RB1 (RB transcriptional corepressor 1)." (PMID 35654783, 2022). "Indeed, hypermethylation of RB1 promoter region due to the overlapping of CpG island 106 is found to be the major epigenetic mechanism underlying decreased retinoblastoma protein expression in Rb tumors." (PMID 35359459, 2022).
retinoblastoma (continued). "When alleles of the RB1 gene are mutated or deleted, RB cells could remain in the inner core layer, initially act as benign precursor “retinoma,” with gene pathogenic variant increased, aggregation and uncontrolled cell proliferation lead to retinoblastoma." (PMID 34336010, 2021). "Retinoblastoma (RB) is a pediatric ocular tumor mostly occurring due to the biallelic loss of RB1 gene in the developing retina." (PMID 32840881, 2021). "Besides tumor initiation by biallelic loss of the RB1 gene, cytogenetic analysis has identified recurrent copy number variants (CNVs) in retinoblastoma tumors, leading to the proposal of several candidate driver genes other than RB1 such as KIF14, MYCN, DEK, E2F3, RBL2/p130, and NGFR." (PMID 33466343, 2021). "Germline alterations in the RB1 tumor suppressor gene predispose patients to develop retinoblastoma (RB) in both eyes." (PMID 34316014, 2021). "Once this molecular testing method is validated in larger multicenter studies, cell-free DNA analysis of retinoblastoma may allow physicians to precisely identify germline RB1 or MYCN mutations and prepare personalized therapy regimens and family genetic counseling." (PMID 34195690, 2021). "Insights gained on small numbers of specimens include the observation that a single eye with multifocal tumors may include more than two identifiable forms of RB1 loss, suggesting intertumoral heterogeneity, and that in wildtype RB1, 6p gain may be sufficient for retinoblastoma tumorigenesis." (PMID 33466343, 2021). "RB is generally described as retinoblastoma predisposition syndrome since germline RB1 mutations lead to a high risk of second primary malignancies." (PMID 33194750, 2020). "However, it is unknown whether orthotopic transplantation and retinal differentiation prior to grafting are required to recapitulate retinoblastoma formation of RB1-deficient ESCs/iPSCs." (PMID 32824373, 2020). "Furthermore, a study of 20 Canadian children with familial Rb found that scheduled early-term (36–38 weeks) delivery following prenatal detection of an RB1 mutation led to an increase in several positive outcome measures including reduced invasive therapy and enhanced vision." (PMID 33143217, 2020). "Knowledge of RB1 led to a paradigm shift in the field of cancer genetics, including widespread acceptance of the concept of tumor suppressor genes, and has provided crucial diagnostic and prognostic information through genetic testing for patients affected by retinoblastoma." (PMID 31683923, 2019). "The pathways affected and interaction with the E2F family of transcription factors, and the role of the RB1 protein product in cell cycle regulation and genomic stability, are the bases for elucidating the molecular etiology of the cellular pathways underlying retinoblastoma tumorigenesis." (PMID 31683923, 2019). "Profiling Retinoblastoma by RNA-seq technology will help fill some of the gaps in our knowledge and provide new insights into how RB1-loss may change the LINC-RNA transcriptome of these aggressive tumors but also to those in more genetically complex adult tumors." (PMID 29868118, 2018). "Retinoblastoma (RB), the most common ocular cancer, mainly occurs due to the biallelic mutation of the RB1 gene on chromosome 13." (PMID 28861107, 2017). "Retinoblastoma (RB), a childhood cancer, is caused by biallelic mutation of the RB1 gene, but its development is not clearly understood." (PMID 28861107, 2017). "Retinoblastoma (RB) is a rare childhood malignant disorder caused by the biallelic inactivation of RB1 gene." (PMID 28575107, 2017). "Retinoblastoma is a rare malignancy, usually diagnosed in early childhood, which originates in the retinal layer of the eye and results from a loss or mutation of both alleles of the RB1 tumor suppressor gene in a retinal progenitor cell during embryonal development." (PMID 26991078, 2016).
retinoblastoma (continued). "Somatic inactivation of both alleles of the RB1 tumor suppressor gene in a retinal progenitor cell through diverse mechanisms including genetic and epigenetic modifications, is the crucial event in initiation of tumorigenesis in most cases of isolated unilateral retinoblastoma." (PMID 25602518, 2015). "Retinoblastoma (RB), an intraocular tumor of childhood, is commonly associated with mutations in the RB1 gene." (PMID 23233783, 2012). "Interestingly, retinoblastoma is caused by mutation in both alleles of the retinoblastoma gene RB1." (PMID 22470431, 2012). "Retinoblastoma develops due to mutation of the Retinoblastoma (RB1) gene and consequent loss of RB protein, which regulates the cell cycle." (PMID 39755235, 2025). "For example, in vitro evaluations of LY3295668 and ENMD-2076, both Aurora kinase inhibitors, have been effective against RB1-mutant small cell lung cancer cells, and LY3295668 was effective at treating RB1-deficient retinoblastoma in vivo." (PMID 40826136, 2025). "One patient with a PGPV of RB1 had a history of retinoblastoma and had already been diagnosed positive for retinoblastoma through confirmatory genetic testing." (PMID 40755265, 2025). "In general, for RB1-associated retinoblastoma, LOH is essential for tumor initiation, inactivating the second RB1 allele after a germline or somatic first hit." (PMID 41009976, 2025). "Retinoblastoma cells exhibit markers of postmitotic cone precursors and rely on cone-specific signaling components, including the TRβ2, for their proliferation and survival, suggesting that the TH signaling pathway may increase susceptibility to the oncogenic effects of RB1 mutations." (PMID 40605078, 2025). "Both copies of the RB1 gene must be inactivated to lead to the development of either heritable or sporadic forms of retinoblastoma." (PMID 41307228, 2025). "In this study, we aimed to detect RB1 mosaicism in a cohort of participants with retinoblastoma using a buffy coat DNA–paired cfDNA assay and to characterize its risk of bilateral disease." (PMID 40338593, 2025). "MYCN amplification can also occur in more typical retinoblastoma (RB) tumors where the RB1 gene is mutated (RB1−/−), resulting in the loss of functional RB protein." (PMID 40317918, 2025). "This cross-sectional study identifies and characterizes RB1 mosaicism in patients with retinoblastoma using a clinical assay that combines plasma cell-free DNA (cfDNA) testing and buffy coat genomic DNA testing." (PMID 40338593, 2025). "Retinoblastoma (RB), a pediatric intraocular malignancy arising from retinal progenitor cells, is characterized by biallelic inactivation of the RB1 tumor suppressor gene." (PMID 40697914, 2025). "Mutations in the tumor suppressor RB1, found in approximately one fourth of HPAP, are common in other malignancies like retinoblastoma, melanoma, and osteosarcoma." (PMID 40826136, 2025). "The Rb1 gene was the first tumour suppressor identified and cloned; its association with the development of retinal cancer gave rise to its name, “RB”, for retinoblastoma." (PMID 39845333, 2025). "Patients with bilateral, unilateral familial, or unilateral multifocal retinoblastoma should undergo RB1 gene sequencing using Sanger sequencing or whole-exome sequencing." (PMID 41009976, 2025). "Many authors have annotated several alterations in the Rb1 gene, not only for retinoblastoma but also for other cancers." (PMID 39845333, 2025). "Retinoblastoma (Rb) is a rare pediatric intraocular malignancy that originates in the developing retina and is driven by biallelic inactivation of the RB1 gene." (PMID 40605078, 2025).